CA9 (carbonic anhydrase 9)
Diseases named in the same sentence as CA9 in open-access papers (continued):
Sharing a sentence is not in itself a finding about the gene and the disease.
tumor (continued). "To confirm that CA9 is overexpressed in tumor tissues compared with para-carcinoma tissues in kidney renal clear cell carcinoma (KIRC), we analyzed the transcriptome data of paired tumor samples and normal tissues in The Cancer Genome Atlas (TCGA)." (PMID 32824856, 2020). "Our data showed that, in contrast to U87‐MG tumour cell line, which reportedly exhibit a strong constitutive expression of CA9 protein, MSC did not bind HS680 in normoxic 2D culture conditions." (PMID 32785979, 2020). "Moreover, one of these studies did observe that the expression of endogenous hypoxia markers CA9, GLUT-1, and MCT-1 were similar in PDX and clinical tumours." (PMID 33322840, 2020). "Beclin-1, ARID1A, CA9 and IDH1 were highly expressed in ICC tumor tissues." (PMID 30849962, 2019). "When we tentatively classified the tumor samples into CA9-positive and -negative groups with a cutoff at staining intensity <20%, 20.7% (37/179) of all TETs were CA9-positive." (PMID 30863491, 2019). "A total of 97 (85.9%) and 77 (68.2%) tumor tissues exhibited positive immunohistochemical staining for Beclin-1 and ARID1A, respectively; 96 (85.0%) and 105 (92.9%) samples stained positive for CA9 and IDH1, respectively." (PMID 30849962, 2019). "The CA9 mRNA and CAIX protein levels of tumor cells correlated with each other, but not with those of the secreted CAIX protein level of the blood of patients." (PMID 30654595, 2019). "At the same time, LDHA, ADM, SLC2A1 and CA9 were also decreased in EP300 knockdown ESCC cells, indicating that EP300 may promote tumor growth and progress via hypoxia in ESCC." (PMID 31632486, 2019). "The tumor hypoxia induces the expression of the CA9 gene in a HIF 1-α dependent manner; on the other hand it was shown that lactate promotes normoxic expression of CA9 genes through HIF 1-α stabilization independently of hypoxia." (PMID 31737570, 2019). "Carbonic anhydrase 9 (CAIX), as a member of the family of metalloenzymes, plays an important role in stabilizing the extracellular pH value by the hydratization of carbon dioxide which influences tumor progression of solid cancers." (PMID 30654595, 2019). "As already mentioned, the presence of CA9 has been widely described in different tumours; however, the protein is not expressed only in normal tissues." (PMID 29745265, 2018). "However, expression of the other hypoxia-specific genes: ERBB3 and CA9, ANGPTL4 was the highest at later stages of tumor development." (PMID 30412628, 2018). "Using the 3D tumor spheroid system with and without CAFs, CA9 expression was further increased 2.5 and 6.2-fold, respectively, over hypoxic monolayer cultures despite these spheroid cultures being grown in normoxic conditions." (PMID 30214007, 2018). "Thus, elevated HIF-1α induces the elevation of multiple target genes, e.g. VEGF, CA9 and MMP2, eventually resulting in aberrant proliferation, invasion and tumor progression." (PMID 29100347, 2017). "Under the control of potential confounding factors including age, tumor stage, metastasis stage and fuhrman grade, CA9 promoter methylation would not be an independent prognostic variable (P = 0.238)." (PMID 29079774, 2017). "Tumor xenografts revealed substantial reductions in tumor growth for both NHE1-ko and CA9-ko." (PMID 28055960, 2017). "The addition of (murine) stromal cells to the injected population for some of the models did not obviously impact the difference in the CA9+ and CA9− fractions of the human tumor cells." (PMID 27901496, 2017). "During responsiveness to Bev, probably because oxygen demand by the tumor decreases, hypoxic markers (HIF-1α and CA9) and the marker for stem cell and vascular proliferation (nestin) are decreased, suggesting that tumor oxygenation is preserved; thus, VEGF and its receptors are relatively reduced." (PMID 29262608, 2017).
tumor (continued). "However, the comparison between the two groups of tumors only showed a limited 3-fold over-expression in CA9 and a 2-fold over-expression in PKD1, in the 21% O2 tumor group as compared to the 3% O2." (PMID 27788227, 2016). "Further mRNA expression of MN/CA9 was detected in cRCC cases whereas normal renal parenchyma from tumor-bearing kidneys had lack of mRNA expression." (PMID 29083380, 2016). "More importantly, and in contrast to the notion that PDAC is a highly hypoxic malignancy, a large proportion of tumor samples presented with either minimal or even lack of CA9 expression in our cohort." (PMID 27637082, 2016). "Because SETDB2 knockdown led to significant inhibition of cell growth, migration and invasion, we further selected six tumor- or differentiation-related genes (WWOX, CADM1/TSLC1, CCDC80, NDRG1, CA9 and FZD9) that have been reported to show altered expression in several cancers including GCs." (PMID 27572307, 2016). "The transplantability of Ca9 was low and tumor formation was not apparent in either Ca9 or Ca9/K17+." (PMID 27512993, 2016). "The expression of CA9 was observed in the tumor cells around a few, not all of the necrotic regions in case 1 (staining: +), and was found in a few spots in cases 5 and 6 despite absence of pseudopalisading necrosis (staining: +)." (PMID 27244880, 2016). "In the present study, we demonstrated that CA9 was overexpressed in hypoxic CRC tumor as compared with normoxia condition." (PMID 26447758, 2015). "The hypoxia-Notch gene subset (HIF-1α/PGK1/VEGF/CA9/OPN-Notch1/Dll1/Hes1/Hes6/Hey1/Hey2) identified by us might hold prognostic implication and offer new opportunities in tumor sub-classification and targeted therapy." (PMID 25734817, 2015). "Numerous studies have investigated the selective application of new treatment modalities based on targeting tumor hypoxia, reporting that hypoxic markers, including HIF-1α, CA9 and VEGF, may be specific and favorable therapeutic targets." (PMID 25789026, 2015). "These include increased expression of a hypoxic gene signature in 10 of 21 patients, increased immunohistochemical staining for CA9 and HIF averaging a threefold increase in 9 of 21 tumours and increased, relative tumour hypoxia as analysed by high-resolution T2 and T2′ mapping." (PMID 25700172, 2015). "Differences in gene expression across all cases when comparing tumor and non-tumor samples were not statistically significant with the exception of CA9 and LOX (p<0.05)." (PMID 26317980, 2015). "For instance, hypoxic stress in the tumor microenvironment evokes Ape/Ref-1 to facilitate the DNA binding activity of HIF-1α, triggering the expression of downstream genes including vascular endothelial growth factor (VEGF), miR210, and CA-9." (PMID 24416428, 2014). "Two genes remained significant in variant of a multivariate model that did not account for tumor stage: ERCC1 (RR = 0.53, 95% CI 0.30–0.96, p = 0.03) and CA9 (RR = 1.79, 95% CI 1.00–3.21, p = 0.05)." (PMID 22848476, 2012). "Carbonic anhydrase 9 (CA9), a glycoprotein belonging to a family of zinc-containing enzymes, is not expressed in most organs or tissues, but it is abundantly expressed in numerous cancers and has been investigated as an endogenous marker for tumor hypoxia." (PMID 23226559, 2012). "We have reported previously that HP5 values made directly in the patient tumor do not correlate well with CA-9 measurements made in individual biopsies from the patient’s tumors." (PMID 24213469, 2012). "Due to the observed effect of Tempol on HIF2α, CA9 and VEGF, all previously reported therapeutic targets for CCRCC tumors, we investigated whether Tempol might have an anti-tumor effect in CCRCC cells." (PMID 23178531, 2012). "Some researches have found that low level of vascular cell adhesion molecule-1 (VCAM-1), E-selectin, angiopoietin 2 (Ang-2) in circulation or carbonic anhydrase 9 (CA9), CD31- microvessel density (CD31-MVD) in tumor tissue can predict beter activity of bevacizumab." (PMID 21762631, 2011).
tumor (continued). "We also stained tumor sections for endogenous markers of hypoxia, HIF-1α and CA-9." (PMID 21647438, 2011). "Consequentially large areas of untreated tumor will stain positive for both HIF-1α and CA-9." (PMID 21647438, 2011). "Any nuclear FIH-1 expression was inversely correlated with CA9 expression (P = 0.04), with tumours negative for CA9 also being twice as likely to express FIH-1 within the nucleus (P = 0.04, odds ratio (OR) = 2.22, 95% confidence interval (CI) = 0.21–0.96)." (PMID 18096060, 2007). "A diffuse cytoplasmic CA9 pattern of expression as a specific feature of VHL cases was observed in our series, differing from the strong membranous staining that we found in undifferentiated tumours." (PMID 15558070, 2005). "CA9, DEC-1 and Hif-1α were expressed in, respectively, 38.3, 76.7 and 46.7% of primary tumours." (PMID 16251878, 2005). "Furthermore, between primary tumours and lymph node metastases a correlation was found for ECP%, TCP%, CA9 and Hif-1α expression (ECP% r=0.51, P<0.001; TCP r=0.77, P<0.001; CA9 and Hif-1α P<0.001)." (PMID 16251878, 2005). "Our results, showing no CA9 accumulation in well-differentiated, non-VHL tumours, are consistent with the fact that VHL mutations have only been reported in the initial progression of a small proportion of PETs." (PMID 15558070, 2005). "The expression of vascular endothelial growth factor (VEGF), HIF-1α, HIF-2α and carbonic anhydrase 9 (CA9) was examined by immunohistochemistry in 45 patients with PETs and compared to microvascular density (MVD), endothelial proliferation, tumour stage and survival." (PMID 15558070, 2005). "Although the majority of the non-replacement CRC liver metastases had CA9 expression at the tumour–liver parenchyma interface and only a minority of the replacement CRC liver metastases, this difference was not significant." (PMID 15054467, 2004). "Since the HIF-2alpha expression in macrophages is induced by hypoxia, and since macrophages in tumours migrate to hypoxic areas, their presence in CRC liver metastases indicates a lower oxygen tension, which accords with the elevated CA9 expression compared to BC liver metastases." (PMID 15054467, 2004). "The expression of LDH was independent of another enzyme involved in tumour acidity and hypoxia, namely CA9, although expression of either of the enzymes related to an ominous prognosis." (PMID 12942121, 2003). "Given that CA9 is induced by hypoxia, we hypothesize that HBO has the capability to downregulate pH‐regulatory proteins such as CA9, MCT4, NHE1, and others, thereby normalizing tumor pH and augmenting tumor therapies." (PMID 40873634, 2025). "Immunofluorescence staining of tumor tissues showed that tumors with TYPE3 blood vessels exhibited significant immune suppression, manifested by lower CD8 levels and significantly higher CA9 staining, whereas, in type 1 and type 2, there was significant lymphocyte infiltration." (PMID 40879489, 2025). "We also observed a significant positive correlation between PRMT5 and CA9 fluorescent staining indicating that PRMT5 is upregulated under hypoxia suggesting that PRMT5 upregulation is clinically relevant and can have implications in governing tumor progression." (PMID 41150697, 2025). "Moreover, if hypoxia in tumor sections is gauged in terms of HIF-dependent responses (e.g., CA9 expression), the results could erroneously exclude regions where HIF became destabilised by acidosis." (PMID 40552983, 2025). "Because 5xHRE/GFP and CA9 are driven by the same promoter, it is not unexpected that their cellular expression is strongly correlated with one another, with a mean Pearson r ̄ of 0.84 (SD = 0.09) across 10 tumor samples." (PMID 37285434, 2023). "There was no expression of the hypoxia marker Carbonic Anhydrase 9 (CA-9) in the tumor cells." (PMID 37098615, 2023). "Unlike the tumor cells, there was no significant increase in the CA9 level in other cell types." (PMID 37194413, 2023).
tumor (continued). "In addition, CA9 can also promote the transport activity of the monocarboxylic transporter (MCT) through non‐catalytic interactions, which can mediate the release of large amounts of lactate and protons from highly glycolytic tumor cells." (PMID 36537608, 2023). "CA9, CD70, and CD147 could represent promising markers to identify tumor-specific EVs in RCC." (PMID 36597108, 2023). "Interestingly in one case, CA9 staining was strong in the capsule sample and in focal lymph node tumor aggregates, whereas the diffuse tumor cell infiltrate in the lymph node was negative (LYWS-1124 A. Feldman)." (PMID 37555981, 2023). "Interestingly, when compared to their individual tumor of origin and not as a cohort, primary cell cultures displayed an even slightly higher mRNA expression of CA9 and HIF1A, while the expression of VHL, VEGFA and VEGFC remained constant." (PMID 35646693, 2022). "Notably, LDHA was found to be expressed mainly in the central hypoxic area of the tumor, colocalized with carbonic anhydrase IX (CAIX or CA9), and some cells invading the corpus callosum (CC), while LDHB was prevalently expressed in peripheral tumor areas and cells invading the CC." (PMID 36278433, 2022). "To validate the in vivo optoacoustic findings and evaluate the effects of Taxotere treatment on tumor vasculature and hypoxia to a greater detail, we conducted immunohistochemical analysis using the endothelial marker CD31 and two hypoxia markers (pimonidazole, CA9)." (PMID 34335966, 2021). "At the initial stage of tumor development, the activation of the genes under consideration provides adaptation to hypoxia, accompanied by a metabolic shift, i.e., the development of glycolysis and a decrease in oxidative phosphorylation (EGLN3, NDUFA4L2, ANGPTL4, CA9, and, apparently, IGFBP3)." (PMID 34046336, 2021). "Tumor tissue microarrays were stained for hypoxia-inducible factor-1α (HIF1A), solute carrier family 2 member 1 (SLC2A1, also known as glucose transporter 1 (GLUT1)), carbonic anhydrase 9 (CA9), and vascular endothelial growth factor A (VEGFA) and classified into low- or high-expression groups." (PMID 33810575, 2021). "We demonstrate for the first time that the expression of the genes CA9, NDUFA4L2, EGLN3, BHLHE41, IGFBP3, and ANGPTL4, regulated by HIF1, is largely correlated, and along with VWF, the expression levels of these genes during tumor progression decreased coordinately." (PMID 34046336, 2021). "However, other studies have suggested that CA9 expression is not directly induced by hypoxia and it is not expressed in all types of tumours." (PMID 31142270, 2019). "Consequently, we believe that CA9 is not an optimal marker for the detection of tumour hypoxia, an important factor in cancer progression, while ERO1α can be a true hypoxic marker." (PMID 31142270, 2019). "In addition, carbonic anhydrase 9 (CA9) and angiopoietin‐related protein 4 (ANGPTL4), proteins known to respond to tumor hypoxia, showed 13‐ and 3.6‐fold increases, respectively, in tumor tissue." (PMID 30459171, 2018). "Similarly, a more potent analog of CA9 inhibitor, SLC-0111, FC12-531A exhibited IC50s ~15-fold lower than SLC-0111 in this 3D tumor spheroid model, demonstrating improved potency in its tumor growth-inhibitory effects over SLC-0111." (PMID 30214007, 2018). "Despite these observations it must be recognized that HIF-1α activity can be influenced by factors other than hypoxia, so this may also influence the correlation between CA9 or GLUT-1 expression and extrinsic markers of hypoxia such as EF5 or pimonidazole in certain tumours." (PMID 27901496, 2017).
tumor (continued). "Similarly to VEGF, transcripts for hypoxia-inducible enzyme carbonic anhydrase 9 (CA9), overexpressed in cancer cells and proposed as a useful marker for hypoxic exposure and tumor aggressiveness were assessed by us (data not shown)." (PMID 26581192, 2015). "Twenty-three of 55 patients with CA9-negative tumors before NAC achieved pCR, and could not be enrolled in the CA9 expression analysis because there was no tumor involvement detected in the resected tissues." (PMID 24893880, 2014). "We evaluated the genes that encode vascular endothelial growth factor A (VEGFA, an isoform of VEGF that is crucial for tumor angiogenesis and plays a key role in endothelial cell proliferation, survival, and permeability), angiopoietin-like 4 (ANGPTL4), and carbonic anhydrase 9 (CA9)." (PMID 24918449, 2014). "Furthermore, we did not detect differences in apoptotic levels between tumours with or without CA9 expression, regardless of the BNIP3 methylation status." (PMID 18728663, 2008). "However, tumour CA9 expression in ESCC patients was not identified as an independent prognostic factor in multivariate survival analysis using Cox proportional hazards analysis." (PMID 18841153, 2008). "Furthermore, a substantial number of lymph node metastases corresponding to primary tumours positive for CA9 or Hif-1α, did not express CA9 or Hif-1α." (PMID 16251878, 2005). "In six tumour samples, CA9 RT–PCR was negative after 40 rounds of amplification." (PMID 12865916, 2003). "Importantly, the activation of CA9 expression depends on the HIF-1α transcription factor activation cascade, which has been identified as a hypoxia-dependent gene that is relevant for the stem cell niche in GB, in which GB cells or GSCs can survive tumor-targeted therapies." (PMID 38139457, 2023). "Importantly, ectopic CA9 could not consistently enhance NK-92 cytotoxicity or degranulation toward tumor target cells." (PMID 36380966, 2022). "However, aspirin did not affect the expression of the tumor-associated CA2, CA9 and CA12." (PMID 33917483, 2021). "So as these genes—CA9, NDUFA4L2, BHLHE41, and EGLN3—are HIF-1α-regulated, from the standpoint of the metastasis biology, a decrease in their expression might suggest a transition of tumor cells to a more malignant condition after an adaptation process that might provoke metastases." (PMID 31936274, 2020). "Our robust in vivo quantitative assay to enrich for CICs could be used to test other cell surface and progenitor markers such as ALDH1, in combination or not with CA9, to potentially identify and further purify a subpopulation of cervix CICs from tumor samples or primary xenografts." (PMID 27901496, 2017). "Importantly, in light of recent concerns raised for the use of tetracylines to achieve gene knockdown, our CA9-ko cells provide confirmation that off target effects due to mitochondria dysfunction were not responsible for reduced tumor growth with CA9 knockdown in previous studies." (PMID 28055960, 2017). "However, although tumor cells grown in transwell coculture with adipocytes expectedly formed significantly larger, disorganized structures, there was no visible increase in CA9 expression compared with spheroids grown under control conditions." (PMID 27458427, 2016). "Furthermore, in hypoxic tumours with positive CA9 expression, a higher proportion of Treg was positive for CXCR4 (median = 18.1%, interquartile range = 9.7% to 40.3%) compared to CA9 negative tumours (median = 4.3%, interquartile range = 2.1% to 19.9%) (P = 0.049)." (PMID 21521526, 2011). "Immunohistochemical analysis showed that the tumor cells were positive for PAX8, CA-9, CD10, and CK7, but negative for CD117 and TFE3." (PMID 41426332, 2025). "IHC indicated that the tumor cells were positive for CK20, CD10 and PAX8, but negative for CK7 and CA9, suggesting the diagnosis of ESC-RCC." (PMID 39080639, 2024).